CRP (C-reactive protein)
Diseases named in the same sentence as CRP in open-access papers (continued):
Sharing a sentence is not in itself a finding about the gene and the disease.
Hypertension (continued). "This is the first nationwide, large cohort study in China to examine the association between CRP levels and risk of hypertension." (PMID 34925916, 2021). "IL-6, TNF-α, and CRP can cause vascular endothelial dysfunction and participate in the occurrence of hypertension during pregnancy." (PMID 34790247, 2021). "On univariate analysis, Cov-AKI was associated with older age (>62 years), hypertension, CRP, MCV, leucocytes, neutrophils, NLR, combined hydroxychloroquine and azithromycin treatment, use of mechanical ventilation, and vasoactive drugs." (PMID 34033655, 2021). "The association between CRP and risk of hypertension has been reported in several cross-sectional and cohort studies." (PMID 34925916, 2021). "This study revealed a weak positive association between CRP levels and future incidence of hypertension in the Chinese population." (PMID 34925916, 2021). "Mirsaeidi, Omar, Ebrahimi, and Campos observed that systemic hypertension in sarcoidosis patients was associated with higher C-reactive protein levels and an increased erythrocyte sedimentation rate, suggesting a correlation with systemic inflammation." (PMID 34768590, 2021). "Differences in CRP are associated with ethnic disparities for a number of chronic diseases, including type 2 diabetes, essential hypertension, sarcoidosis, and lupus erythematosus." (PMID 34733313, 2021). "Bilirubin was nonetheless inversely associated with HOMA-IR, CRP, and with three components of MS, i.e., large WC, high blood pressure, and high triglycerides." (PMID 34202304, 2021). "Plasma levels of lipids, CRP, and IL-6 will be reduced by daily consumption of barberry in patients with hypertension and other cardiovascular risk factors." (PMID 33246500, 2020). "Elevated levels of CRP have been associated with increased cardiovascular risks like left ventricle hypertrophy and hypertension in children and adults." (PMID 32295034, 2020). "OSA severity measures such as AHI, ODI, and lowest SaO2, were independently associated with high risk hs‐CRP level (>3 mg/L) after adjusting for age, BMI, hypertension, fasting glucose, LVEDD, IVST, and supine sleep time." (PMID 32458487, 2020). "The delirium group had a higher average age and C-reactive protein level, and lower hematocrit, eGFR, and albumin readings, and more underlying hypertension." (PMID 33189145, 2020). "Prior work indicates that the C-reactive protein (CRP) is an inflammatory precursor, directly linked in the later stage of hypertension to coronary remodeling." (PMID 32762480, 2020). "In a nested case-control study, interleukin (IL)-6 was less highly related to the risk of developing hypertension than hs-CRP." (PMID 32292598, 2020). "A prospective cohort study shows that C-reactive protein (CRP) levels are associated with future development of hypertension, which suggests that hypertension is in part an inflammatory disorder." (PMID 31941463, 2020). "Alternatively, Nesami and co-workers found CoQ10 supplementation to be effective in decreasing some pro-inflammatory factors like IL-6 and CRP, in association with increasing adiponectin levels in patients with mild hypertension." (PMID 32375340, 2020). "Lastly, male sex (OR, 2.03; 95% CI, 1.14 to 3.61), hypertension (OR, 2.71; 95% CI, 1.31 to 5.58) and hs-CRP (OR, 1.21; 95% CI, 1.02 to 1.49) were independent risk factors for C-IFG/IGT." (PMID 32295016, 2020). "According to prospective studies investigating inflammatory markers, high-sensitivity C-reactive protein (hs-CRP) is related to the risk of developing hypertension." (PMID 32292598, 2020). "In this study, after adjusting for age, gender and BMI, the E2 allele was associated with high CRP-values after the two treatment periods and with hypertension." (PMID 32646381, 2020). "In univariate linear regression analysis, lower baseline eGFR was significantly associated with older age, male gender, higher CRP, higher weight and presence of hypertension." (PMID 32762646, 2020).
Hypertension (continued). "For both sexes, higher SU quartile values were associated with BMI (p < 0.0001 in both men and women), hs-CRP (p = 0.007 in men and p < 0.0001 in women), and the prevalence of hypertension (p = 0.003 in men and p < 0.0001 in women)." (PMID 32087742, 2020). "Acute inflammation has been most often associated with circulating levels of CRP, and even predicts hypertension, suggesting hypertension is part of an inflammatory cascade." (PMID 33066786, 2020). "In the univariate linear regression analysis of patients with subsequent AHREs, prior AF (p = 0.008), CHF (p = 0.001), hypertension (p = 0.050), and hs-CRP (p = 0.037) showed significant associations with AHREs burden." (PMID 33207668, 2020). "All of the human trials sought to elucidate the effect of honey on the modulating parameters associated with cardiovascular risk factors, such as body mass index (BMI), C-reactive protein elevation, hypertension, and abnormal lipid profile." (PMID 32455701, 2020). "Higher SU quartiles were in both sexes associated with BMI, hs-CRP, and the prevalence of hypertension, and in women, they were also associated with the prevalence of dyslipidemia." (PMID 32087742, 2020). "Higher odds of high blood pressure were associated with leptin (1.57 (1.08, 2.27)), and higher odds of abdominal obesity were associated with CRP (2.14 (1.33, 3.45)) only in men." (PMID 33374992, 2020). "Elevated levels of proinflammatory markers, such as c-reactive protein (CRP), are associated with increased prevalence of arterial stiffness, high blood pressure, and CVD development." (PMID 32486335, 2020). "Older-age was consistently associated with nutrition-related chronic disease and being overweight was associated with hypertension, elevated hs-CRP, and type 2 diabetes." (PMID 31469876, 2019). "DM, systemic hypertension, dyspnea, thoracic pain, temperature and CRP levels were the clinical features associated with worse clinical outcomes." (PMID 31718571, 2019). "It has also been reported that CRP is significantly associated with increased risk of the development of hypertension, suggesting that hypertension is, at least in part, an inflammatory disorder." (PMID 30934586, 2019). "In crude models, higher prevalence of prehypertension/hypertension were associated with increasing levels of hs-CRP (all OR > 1, P < 0.05)." (PMID 31340788, 2019). "C-reactive protein (CRP), a marker of inflammation, is considered to be significantly associated with the occurrence and progression of hypertension." (PMID 30984420, 2019). "IL-6 is a potent inducer of hepatic CRP and has been implicated in cardiovascular atherosclerotic risk, dyslipidemia and hypertension." (PMID 31293514, 2019). "In the univariate analysis, placental abruption was significantly associated with lower maternal age, arterial hypertension, and higher gestational age at delivery, as well as higher neonatal weight and higher leukocyte, CRP, and fibrinogen serum levels." (PMID 30970668, 2019). "CRP levels have been positively associated with increased oxidative stress and cardiovascular diseases such as atherosclerosis and hypertension." (PMID 31590321, 2019). "Age, body mass index (BMI), smoking, hypertension, hyperthyroidism, malignancy, increased levels of C-reactive protein, and triglycerides are associated with higher levels of cystatin C39,40." (PMID 30723243, 2019). "There was a positive association between the higher quartiles of CRP and the presence of hypertension after adjusting for lifestyle-related variables." (PMID 31048753, 2019). "Chronic inflammation causes the increase of oxidative stress, CRP synthesis, and pro-inflammatory cytokines production and this is associated with endothelial dysfunction in hypertension." (PMID 30935055, 2019).
Hypertension (continued). "For example, excess sodium consumption is related to hypertension risk, and excess sugar consumption is related to central obesity and elevated high sensitivity-C-reactive protein (hs-CRP), all of which are related to CVD." (PMID 31469876, 2019). "Several factors have been linked to differences in postpartum CRP level including formula versus breastfeeding, vaginal versus caesarean delivery, gestational diabetes and hypertension." (PMID 32082531, 2019). "Hs-CRP was demonstrated to serve as an indicator to identify the risk of cardiovascular events in patients with high blood pressure." (PMID 31340788, 2019). "C-reactive protein (CRP), an acute phase reactant protein, is an independent risk factor for cardiovascular disease including hypertension, and previous RCTs indicated that vitamins and minerals had a significant lowering effect on CRP." (PMID 30081527, 2018). "Hypertension, presence of metabolic syndrome, body mass index and treatment to high blood pressure were directly associated with CRP levels, while treatment with statins was inversely associated." (PMID 29558396, 2018). "Lower plasma Cr level was associated with hyperglycaemia, hyperinsulinemia, hypertension, insulin resistance and CRP." (PMID 29975702, 2018). "This study shows that high C-reactive protein (CRP), is associated with increased risk of developing hypertension among healthy women." (PMID 30886961, 2018). "Mean RDW quartile, age, hypertension, albumin level, Charlson Comorbidity Score and CRP level were identified as potential risk factors for cerebral infarction in the univariate Cox proportional hazard model." (PMID 29141483, 2017). "CRP levels were associated with greater odds for having hypertension and hyperglycemia compared to AHI." (PMID 28947597, 2017). "CRP levels were also associated with greater odds for having hypertension and hyperglycemia compared to AHI." (PMID 28947597, 2017). "Given that IL-6 increases the CRP levels, IL-6 is also likely to act similarly and cause hypertension in patients with PCOS." (PMID 28042549, 2017). "The higher quartile of CMV IgG titer and CRP level were associated with the incidence of hypertension and the progression of hypertension and hypertensive TOD." (PMID 28837559, 2017). "TnT had a direct positive association with age (p<0.0001), hypertension (p=0.0159) and the serum level of CRP (p=0.0107) and a tendency for a positive association with male sex (p=0.0569)." (PMID 28578371, 2017). "This correlation was observed even after adjustment for traditional cardiovascular risk factors, including hypertension, smoking, DM, dyslipidemia, and hs-CRP levels." (PMID 29109596, 2017). "Congestive heart failure and the clinical variables high blood pressure and CRP in the upper tertile associated significantly with admission to hospital." (PMID 28880941, 2017). "Higher levels of HRPI are associated with abdominal girth, high blood pressure, high C-reactive protein concentrations and allostatic load." (PMID 28434029, 2017). "CRP is considered as an independent predictor of cardiovascular disease and has been associated with increased risk for development of hypertension." (PMID 26989902, 2016). "Incidence of CKD was significantly associated with age, persistently high CRP, hypertension, and use of NSAIDs at study baseline." (PMID 27537204, 2016). "These nominally significant findings, on the one hand, are in line with numerous epidemiological studies that have highlighted an association between elevated CRP and an increased risk of hypertension." (PMID 27327646, 2016). "For instance, one study found an association between CRP loci and hypertension in Asian individuals." (PMID 27327646, 2016). "The logistic regression analysis revealed that CAD significantly associated with age, gender, hs-CRP, hypertension, LDL-C, and DPP4." (PMID 27654253, 2016).
Hypertension (continued). "Our study affirms the association of C-reactive protein in essential hypertension as is evident from the higher levels of CRP in patients as compared to that of controls." (PMID 26989902, 2016). "High-risk levels of glycosylated Hb, waist circumference, CRP, fibrinogen, and hypertension grade 2 (marginally only) were significantly associated with increased risks of reporting poor general health in the female sample." (PMID 26121035, 2015). "Mutation-carriers had lower CRP levels and a higher rate of cure of hypertension after adrenalectomy." (PMID 26066391, 2015). "It should also be noted that in a recent study conducted with the same population, we found the association between smoking quantity and hypertension to be mediated by C-reactive protein, an inflammatory marker." (PMID 25874685, 2015). "In subjects without AF, several epidemiological studies have established an association of CRP with the occurrence of hypertension while oxLDL has been linked to the development of subclinical vascular disease." (PMID 26229238, 2015). "Numerous studies have reported the associations between the elevated levels of Ox-LDL and CRP and increased likelihood of cardiovascular events, including hypertension and endothelial dysfunction." (PMID 25864817, 2015). "We have also demonstrated that baseline plasma levels of CRP and oxLDL are associated with the risk for incident vascular disease (hypertension) during a median 3-year follow-up in lone AF patients, but not in healthy controls." (PMID 26229238, 2015). "Lower CRP levels in mutation-carriers relates to a higher rate of cure of hypertension after adrenalectomy." (PMID 26066391, 2015). "Further studies should be performed to find the true nature of association between hs-CRP and hypertension." (PMID 25237581, 2014). "Some conventional risk biomarkers (smoking, hypertension, hyperlipidemia, HbA1c level and CRP level) were independently associated with PAD." (PMID 24655436, 2014). "In RA patients, anti-hnRNP B1 autoantibodies correlated significantly with C-reactive protein levels and erythrocyte sedimentation rate, while in patients with SSc it was associated with features of arterial wall stiffness and presence of hypertension." (PMID 24883333, 2014). "Insulin resistance and increased CRP concentrations have been shown to be significantly associated with several cardiovascular risk factors, such as age, smoking, hypertension, exercise, plasma lipids, homocysteine, and body mass index (BMI)." (PMID 24795503, 2014). "Multiple population-based human studies have established a strong association between increasing levels of serum C-reactive protein, uric acid and subsequent development of hypertension." (PMID 25237581, 2014). "We aimed to investigate the association between mental well-being with presence of hypertension, hyperuricemia and hs-CRP levels." (PMID 25237581, 2014). "Baseline body mass index, FPG, HbA1c, CRP, hypertension, and female gender were all significantly associated with incident T2DM." (PMID 24819157, 2014). "Higher CRP and IL-6 concentrations were associated with increased risk of hypertension in both white and black women." (PMID 25329057, 2014). "Studies showed that high-sensitivity C-reactive protein (hs-CRP) acts as an inflammatory marker, is associated with increasing cardiovascular risks, and plays an important role in hypertension and atherosclerosis." (PMID 24349092, 2013). "Serum CRP is widely believed to be an independent predictor of heart attack and stroke as well as an independent risk factor for hypertension." (PMID 23978069, 2013).
Hypertension (continued). "Polymorphisms in AGTR1 and especially the C allele of rs5186 (+1166A>C) have been associated with hypertension and the A allele of rs5186 has been associated with higher serum levels of high-sensitivity C-reactive protein (CRP) and inflammation." (PMID 23437094, 2013). "Hypertension is a significant predictor of cardiovascular events and is strongly association with inflammation by CRP." (PMID 23978069, 2013). "Other important factors, such as affliction to heart failure, chronic kidney disease and hypertension didn’t show any statistically significant associations with CRP levels." (PMID 24523776, 2013). "Bautista reviewed multiple studies and reported a positive association between hypertension and some proinflammatory markers including C-reactive protein (CRP), interleukin-6 (IL-6), and tumor necrosis factor alpha (TNF-α)." (PMID 23691280, 2013). "The associations of depressive symptoms and 24-hour hypertension were slightly attenuated after further adjustments for other risk factors including body mass index, CRP, total/HDL cholesterol, and glucose." (PMID 22028954, 2012). "Associations of CFH genetic variants genotypes with blood pressure and hypertension stratified by C-reactive protein levels." (PMID 22848687, 2012). "Female gender, low income, hypertension, and high BMI were associated positively with the odds of CRP elevation being repeated, although the magnitude of the association with BMI was smaller in men than in women." (PMID 22558327, 2012). "For example, depressive symptoms were associated with body mass index and CRP, both of which have been implicated in hypertension risk." (PMID 22028954, 2012). "We identified high CRP and high blood pressure as clinical markers associated with ARF in TMA patients." (PMID 22292070, 2012). "High blood pressure as well as high CRP serum levels on admission are associated with renal insufficiency in TMA." (PMID 22292070, 2012). "High CRP serum levels and high blood pressure indicate a predisposition for ARF and persistent renal insufficiency." (PMID 22292070, 2012). "On multiple regression analysis, only older age, higher HbA1c, hypertension, current smoking and higher CRP were significantly associated with albuminuria." (PMID 21595912, 2011). "Older age, higher HbA1c, hypertension, higher C-reactive protein and current smoking were independently associated with albuminuria on multiple regression." (PMID 21595912, 2011). "C-reactive protein (CRP) is an important risk factor for many diseases, including stroke and hypertension." (PMID 19240794, 2009). "It should be noted that this was for the unadjusted measure of CRP, i.e. some of these reductions in the gradients were due to established risk factors known to be associated with CRP such as smoking, hypertension, and BMI." (PMID 18518944, 2008). "Depression, as measured by RDS-4, and inflammation, as measured by CRP concentration, together explained 11.7% of the association between chronic pain and risk of hypertension; of the two significant mediators, depression accounted for a large proportion of the mediation effect." (PMID 41243808, 2026). "In addition, higher CRP z-scores were positively associated with the risk of abdominal obesity, dyslipidemia, hypertension and of showing several elevated components of the MetS." (PMID 39862247, 2025). "This is contrary to most studies, which have found that CRP is associated with hypertension." (PMID 39613339, 2025). "Still, characteristics of the cases and controls, and differences between them regarding classical NVAF risk factors (e.g., age, sex, hypertension, CRP, indicators of the renal function, NT-proBNP, LDL-C, and triglycerides) were generally in line with the expectations." (PMID 41300894, 2025). "Additionally, for patients at high risk of TEs (such as elevated CRP level, hypertension, large number of comorbidities and mediastinal lymphadenopathy), the necessity of primary thromboprophylaxis should be considered." (PMID 40751559, 2025).